ABCA1 (ATP binding cassette subfamily A member 1)
Diseases named in the same sentence as ABCA1 in open-access papers (continued):
Sharing a sentence is not in itself a finding about the gene and the disease.
glioma (continued). "ABCA1 expression in U87MG cells was potently induced by 25-OHcholesterol, a natural LXR ligand and oxysterol synthesized and secreted by glioma cells." (PMID 26002572, 2015). "Overexpressed ABCA1 reduced the drug activity of TMZ in inhibiting the growth of glioma cells, while ABCA1 knockdown followed by treatment with TMZ remarkably increased the death rate of glioma cells and suppressed the cell clone forming." (PMID 37749600, 2023). "The transcript level of ABCA1 significantly elevated across the TMZ-resistant glioma cells in contrast with non-resistant cells." (PMID 37749600, 2023). "The results of analyzing the protein expression levels of ABCA1 with Western blotting showed that ABCA1 in TMZ-resistant glioma cells was significantly higher than that in non-resistant glioma cells." (PMID 37749600, 2023). "In conclusion, we revealed that the ABCA1 transporter restrained the chemosensitivity of TMZ and enhanced immune cell infiltration in glioma, intimating that TMZ combined with ABCA1 antagonists was a potential approach to improving the therapeutic efficacy of glioma." (PMID 37749600, 2023). "Nonetheless, studies are still fewer on ABCA1 expression and TMZ resistance in glioma." (PMID 37749600, 2023). "We started with using the ABCA1 gene expression data and corresponding clinical information to assess the overall survival (OS), disease-specific survival (DSS), and progression-free interval (PFI) of glioma patients in the TCGA database." (PMID 37749600, 2023). "DDT also increases Aβ levels in H4 glioma cells with a APPSwe transgene via elevation of APP and BACE1, while decreasing the levels of Aβ-clearing ATP-binding cassette transporter A1 (ABCA1) and inhibiting the activity of Aβ-degrading insulin-degrading enzyme (IDE)." (PMID 32218337, 2020). "Cells with CRISPR-mediated knockdown of LXRβ, but not ABCA1, had decreased cell cycle progression and cell survival, and decreased feedback repression of the mevalonate pathway in densely-plated glioma cells." (PMID 31664073, 2019). "We saw that a synthetic LXR agonist, GW396533, increased ABCA1 RNA levels but did not change either NR1H2 or NR1H3 (the genes encoding LXRβ and LXRα) in either of two different glioma lines, TS543 and TS576." (PMID 31664073, 2019). "Besides, we detected relatively higher mRNA and protein levels of ABCA1 in TMZ-resistant glioma cells (U118-R and T98G-R) compared to the non-resistant glioma cells (U118 and T98G)." (PMID 37749600, 2023).
hypoalphalipoproteinemia (13 papers, 2009 to 2025). A metabolic disorder characterized by deficiency of high density (alpha) lipoprotein in the blood. "Heterozygous ABCA1 loss-of-function variant carriers have moderate-to-severe hypoalphalipoproteinemia with increased ASCVD risk." (PMID 40004987, 2025). "An association has been reported between the ABCA1 R230C polymorphism with hypoalphalipoproteinemia." (PMID 37988669, 2023). "There is evidence showing that disruption in ABCA1 function, which can be the result of mutation in this gene, can lead to familial hypoalphalipoproteinemia that is characterized by low HDL and increased deposition in cholesteryl esters in several tissues and cells." (PMID 26788366, 2015). "Moreover, large-scale deletions of the human ABCA1 gene are a causative factor for hypoalphalipoproteinemia, a disease that is characterized by the complete absence of the apolipoprotein AI and extremely low levels of plasma high-density lipoprotein (HDL) cholesterol." (PMID 32770942, 2020). "In 288 patients with hypoalphalipoproteinemia, we identified three rare, large-scale deletions in ABCA1 in four individuals by applying specialized bioinformatic tools to NGS data." (PMID 29866657, 2018). "We evaluated targeted, next-generation sequencing data from patients with very low levels of HDL cholesterol (i.e., hypoalphalipoproteinemia) with the VarSeq-CNV® caller algorithm to screen for CNVs that disrupted the ABCA1, LCAT, or APOA1 genes." (PMID 29866657, 2018). "Analysis of LipidSeq output with the VarSeq-CNV® caller algorithm identified four hypoalphalipoproteinemia patients as carriers of large-scale deletions in ABCA1." (PMID 29866657, 2018). "Genetic mutations in ABCA1, apoA-1, and LCAT are associated with familial hypoalphalipoproteinemia." (PMID 32455724, 2020). "Previously, large-scale deletions in candidate HDL genes had not been associated with hypoalphalipoproteinemia; our findings indicate that CNVs in ABCA1 may be a previously unappreciated genetic determinant of low levels of HDL cholesterol." (PMID 29866657, 2018). "Furthermore, the interpretation might be complicated by a lack of evidence in the association of high cancer risk with genetic forms of hypoalphalipoproteinemia, namely familial LCAT deficiency, familial HDL deficiency due to ABCA1 gene mutations, and familial apoAI deficiency." (PMID 34065252, 2021). "ATP-binding cassette transporter A1 (ABCA1) is a membrane integral protein which plays a vital role in High Density Lipoprotein (HDL) metabolism and exerts a protective effect against Hypoalphalipoproteinemia (HA) by mediation of rate-limiting step in HDL biogenesis." (PMID 28090279, 2017). "CNVs disrupting ABCA1, APOA1, or LCAT in individuals with hypoalphalipoproteinemia have not yet been reported." (PMID 29866657, 2018).
steatosis (13 papers, 2007 to 2024). Increased lipid within the cytoplasm of cells. "One of the SNPs showing consistent association with biopsy results was ABCA1 rs2230806, which was also the top SNP associated with change in steatosis." (PMID 30065651, 2018). "SNPs associated with change in steatosis score were: ABCA1 rs2230806 (β = 0.35, p = 0.0087) and RETN rs4804765 (β = −0.32, p = 0.033)." (PMID 30065651, 2018). "BBR can reduce steatosis by increasing ATP-binding cassette transporter A1 (ABCA1) protein levels through PKCδ to reduce the phosphorylation of serine residues in ABCA1." (PMID 36814494, 2023). "Four genes had lower expression in steatosis (ABCA1, MTR, MTHFR, and PLG) and five genes had higher expression (SEPHS2, DIO1, HBB, SAA1, and SAA2) in the “selenoprotein micronutrient network” pathway." (PMID 34869521, 2021). "In detail, we found the down expression of FABP1 (40 times) and APOC3 (11.98 times), PPARGC1A and GK (11 times), ABCA1 and SRBF2 (3 times) compared to the steatosis control." (PMID 36770927, 2023). "The treatment with curcumin-andrographolide in association maintained the ability to regulate in a negative manner FABP1 (15.96 times), PPARGC1A (7.85 times), GK and ABCA1 (4 times), and APOC3 (2.04 times) in respect to the steatosis control." (PMID 36770927, 2023). "In our experiments, the downregulation of genes involved in lipid/cholesterol metabolism and transport (such as FABP1, APOC3, PPARGC1A, GK, ABCA1, and SRBF2) induced by curcumin treatment could explain the observed reduction of steatosis and lipid content." (PMID 36770927, 2023). "It is also indicated that the absence of ABCA1 lead to steatosis in metabolic liver disease." (PMID 36005631, 2022). "In the present study, we found that the mRNA and protein expression of PPAR-α and ABCA1 decreased in the HFD-induced NASH model than the control group, and also in the PA/OA-induced steatosis cell model, while KP could increase their expression both in vivo and in vitro." (PMID 34262459, 2021). "The reduction in ABCA1 expression is also consistent with lower plasma HDL levels observed in the LRP1 NPxY mutant mice, whereas the lower expression levels of the lipogenic genes may account for the reduced steatosis and lower inflammation in the livers of HFHC diet-fed LRP1 NPxY mutant mice." (PMID 33500241, 2021).
glioblastoma (12 papers, 2019 to 2026). The most malignant astrocytic tumor (WHO grade IV). "Ectopic expression of the ABCA1/G1 ligand ApoA1 enhanced cholesterol efflux from TAM in the glioblastoma microenvironment and led to tumor clearance." (PMID 39196415, 2024). "Conversely, another study found reduced cholesterol efflux from human glioblastoma U373-MG astrocytoma cells to AD CSF compared to control CSF after ABCA1/G1-dependent pathway stimulation." (PMID 39764088, 2024). "Consistent with previous findings, human A172 glioblastoma astrocytes showed a higher capacity for inducing ABCA1/G1-mediated cholesterol efflux to CSF compared to neurons." (PMID 39764088, 2024). "LXRβ gene expression poorly correlates with ABCA1 in glioblastoma patients, and expression of each gene correlates with poor patient prognosis in different prognostic subtypes." (PMID 31664073, 2019). "In this report, we show that high cell density induces ABCA1 expression in glioblastoma cells, enabling them to get rid of excess cholesterol generated by an activated cholesterol biosynthesis pathway." (PMID 31664073, 2019). "To address this, we first looked at NR1H2 and ABCA1 gene expression in the TCGA Glioblastoma data set and saw that they are only very weakly correlated." (PMID 31664073, 2019). "A dissection of the relationship between NR1H2 and ABCA1 gene expression in the TCGA Glioblastoma data set shows that only very weak correlation, which is in congruence with our experimental findings." (PMID 31664073, 2019). "To further define ABCA1-independent roles of LXRβ in glioblastoma, we compared gene set enrichment analyses (GSEA) for crLXRb-1 and crNT cells at low and high cell density." (PMID 31664073, 2019). "In glioblastoma, we found that low ABCA1 expression in GBM patients was associated with poor DFS (P = 0.07), but the expression level of ABCA1 in GBM tumour tissues was greater than that in corresponding normal tissues (P < 0.05)." (PMID 40297807, 2025). "For example, after engulfing CHOL-rich myelin debris, TAMs turned into LLMs and then transferred myelin-derived lipids to glioblastoma (GBM) cancer cells via an LXR/Abca1-dependent way, thereby supporting the metabolic demands of mesenchymal GBM." (PMID 40868150, 2025). "We evaluated the ability of human A172 glioblastoma astrocytes and SH-SY5Y neurons to mediate cholesterol efflux to CSF under basal conditions and following stimulation of the ABCA1- and ABCG1-dependent pathways." (PMID 39764088, 2024).
Hypertension (12 papers, 2012 to 2022). The presence of chronic increased pressure in the systemic arterial system. "First of all, this study only mentioned the association of ABCA1 gene polymorphisms with hypertension." (PMID 35669754, 2022). "Hypertension was more prevalent in ABCA1 mutation carriers (p = 0.002) and LCAT mutation carriers (p = 0.02)." (PMID 24842300, 2014). "Therefore, we performed a case-control study of the Chinese Han population to estimate the risk of hypertension with polymorphisms of ABCA1 in Zhejiang province and predict the genetic risk of this condition." (PMID 35669754, 2022). "Interestingly, hypertension was more prevalent in both ABCA1 and LCAT mutation carriers, but seemed better regulated in ABCA1 mutation carriers." (PMID 24842300, 2014). "In the collecting duct, CsA may cause hypertension by stimulating the epithelial Na+ channel through a pathway associated with inhibition of ATP-binding cassette A1 (ABCA1)." (PMID 25013642, 2012). "In addition, another report demonstrated that the -14 C→T polymorphism of the ABCA1 gene is a determinant of blood pressure and the development of hypertension in Japanese individuals, and nine lipid-related SNPs have interactions with the effect of cigarette smoking on blood pressure levels." (PMID 34975757, 2021). "This study explored the association between single-nucleotide polymorphisms (SNPs) in the adenosine triphosphate (ATP)-Binding Cassette Subfamily A1 (ABCA1) gene and hypertension among Chinese Han adults." (PMID 35669754, 2022). "The results of the relationship between the polymorphisms of rs2297406, rs2472433, rs2472510, and rs2515614 in ABCA1 and hypertension in southeastern China would provide a theoretical basis for genetic screening and disease prevention." (PMID 35669754, 2022). "The relationship between different gene models under each ABCA1 locus and hypertension was analyzed by binary logistic regression." (PMID 35669754, 2022). "Some research studies proposed that the abnormal ABCA1 cholesterol transporting function may cause hypertension by stimulating epithelial sodium channels (ENaCs), the vital components in the regulation of total body Na+ homeostasis, and might also lead to the occurrence of hypertension." (PMID 35669754, 2022). "This study explored the significant relationship between four SNPs (rs2297406, rs2472433, rs2472510, and rs2515614) in ABCA1 with hypertension in the southeast Chinese Han population." (PMID 35669754, 2022). "Recent evidence has shown that the expression of ABCA1 is significantly decreased in patients with hypertension, and the outflow of cholesterol to apo-A1 leads to increased carotid intima-media thickness, and promotes arterial hypertension." (PMID 34026879, 2021). "Eventually we identified a set of SNPs and environmental factors: rs5805 in the SLC12A3, rs12654264 in the HMGCR, rs2065412 and rs414936 in the ABCA1, rs96418 in the ZPR1 gene, waistline, degree of education, exercise frequency, hypertension, and the intake of meat." (PMID 32600448, 2020).
hypertriglyceridemia (12 papers, 2006 to 2024). A laboratory test result indicating elevated triglyceride concentration in the blood. "Compared with the control group, the ABCA1 C69T gene mutation significantly reduced the risk of hypertriglyceridemia in diabetic patients (dominant model: WMD = 0.66, 95% CI = 0.52–0.8, P < 0.0001, I2 = 60%; recessive model: WMD = 0.47, 95%CI = 0.11–0.83, P = 0.01, I2 = 32%)." (PMID 31010439, 2019). "In the present study, in a prediabetic HHTg model with severe hypertriglyceridemia we observed markedly increased expression of Abcb1b, Abca1, and Abcg8 genes and decreased expression of Abcb1a and Abcg5 genes." (PMID 37077818, 2023). "ABCA1 C69T gene mutation significantly reduced the risk of hypertriglyceridemia in diabetic patients than that in the non-diabetic subjects." (PMID 31010439, 2019). "ABCA1 C69T gene mutation significantly reduced the risk of hypertriglyceridemia in diabetic patients than that in non-diabetic subjects.." (PMID 31010439, 2019). "Reduced ABCA1 activity, as observed in T2DM, limits cholesterol transport from cells to small HDL particles, contributing to hypertriglyceridemia even at low plasma APOC3 levels, emphasizing the importance of ABCA1 in lipoprotein metabolism and cardiovascular health." (PMID 39684468, 2024). "ABCA1-dependent efflux was also increased using apoB-depleted serum from T2DM patients with hypertriglyceridemia compared to T2DM patients without hypertriglyceridemia." (PMID 36837872, 2023). "In addition, CKN activated ABCA1 by promoting LXRα nuclear translocation without undesirable adverse effects such as liver fat deformation or hypertriglyceridaemia." (PMID 37322486, 2023).
ischemic stroke (12 papers, 2007 to 2025). A stroke disorder caused by obstruction of blood flow to the brain, due to thrombotic (local blood clot formation) or embolic (due to a blood clot or other material traveling from another site) event. "As the control population of one study deviated from HWE, this study was omitted in the further analysis but there was still significant association between ABCA1 R219K with ischemic stroke for 3 genetic models (p<005)." (PMID 32292824, 2020). "ABCA1 R219K has been suggested as a risk factor for ischemic stroke, but the results remain inconclusive in the Chinese population." (PMID 32292824, 2020). "The results found that the meta-analysis of the correlation between the ABCA1 R219K and ischemic stroke susceptibility remained unchanged in all genetic models." (PMID 32292824, 2020). "This study aimed to assess the association between ABCA1 R219K and ischemic stroke using meta-analysis." (PMID 32292824, 2020). "This study has assessed the distribution of ABCA1 polymorphisms and haplotype arrangements in patients with ischaemic stroke and compared them to an appropriate control group." (PMID 17553166, 2007). "We studied four common polymorphisms in ABCA1 gene: G/A-L158L, G/A-R219K, G/A-G316G and G/A-R1587K in 400 Caucasian ischaemic stroke patients and 487 controls." (PMID 17553166, 2007). "The aim of this study was to assess the distribution of different polymorphisms and haplotype arrangements of the ABCA1 gene, and any association with lipid profile, in a series of well-phenotyped ischaemic stroke patients and unaffected control subjects." (PMID 17553166, 2007). "The only published study in ischaemic stroke on 244 Hungarian patients suggests a protective role for the ABCA1-R219K and V771M polymorphisms." (PMID 17553166, 2007). "The most notable finding was the interaction between the ABCA1 rs1883025 variant and dietary protein intake, where T allele carriers exhibited a reduced risk of ischemic stroke despite their low HDL cholesterol phenotype when their protein consumption was high." (PMID 40077648, 2025). "For instance, ABCA1 rs1883025 T allele carriers may benefit from a high-protein diet to mitigate ischemic stroke risk, while APOA5 rs651821 carriers should be cautious about high-fat intake due to its potential to exacerbate CAD risk." (PMID 40077648, 2025). "Taking together, the meta-analysis revealed that ABCA1 KK+RK carriers might have decreased risk of ischemic stroke in Chinese populations." (PMID 32292824, 2020). "The main findings of this meta-analysis are that the allele K might be a protective factor for the IS and the ABCA1 KK+RK carriers might have decreased risk of ischemic stroke in Chinese populations." (PMID 32292824, 2020). "We also found that the allele K of ABCA1 R219K might be a protective factor for IS and, particularly, the KK+RK carriers might have decreased risk of ischemic stroke in Chinese populations." (PMID 32292824, 2020). "This meta-analysis suggested that ABCA1 R219K polymorphism might be a protective factor against developing IS, indicating this SNP may contribute to the pathogenesis of ischemic stroke and might be potentially used as a biomarker to predict the susceptibility to ischemic stroke." (PMID 32292824, 2020). "In conclusion, this study highlights significant interactions between dietary protein and fat intake and HDL-associated genetic variants, particularly the ABCA1 rs1883025 and APOA5 rs651821 variants, in modulating ischemic stroke and CAD risk, respectively." (PMID 40077648, 2025). "Through literature searching, 68 publications relevant to ABCA1 gene and ischemic stroke were identified." (PMID 32292824, 2020). "CKN alleviates ischemic stroke injury via LXRα/ABCA1 activation and TLR4 inhibition." (PMID 40880849, 2025).